MPP3 (MAGUK p55 scaffold protein 3)
Description:
Participates in cell spreading through the phosphoinositide-3-kinase (PI3K) pathway by connecting CADM1 to DLG1 and the regulatory subunit of phosphoinositide-3-kinase (PI3K). Stabilizes HTR2C at the plasma membrane and prevents its desensitization. May participates in the maintenance of adherens junctions (By similarity).
Synonyms: DLG3
Tractability: Antibody: UniProt places it where antibodies can reach, with high confidence; its Gene Ontology location is reachable by antibodies, with high confidence. PROTAC: ubiquitination databases record sites on it; its protein half-life has been measured.
Gene: Protein-coding gene on chromosome 17 (43,800,799 to 43,833,170, reverse strand). Ensembl gene ENSG00000161647.
Subcellular location: Cell membrane; Apical cell membrane; Cell junction, adherens junction
Subcellular location (Human Protein Atlas): Cytosol; Nucleoplasm
Gene Ontology:
Molecular function: protein binding; PDZ domain binding
Cellular component: apical plasma membrane; plasma membrane; adherens junction; cell-cell junction
Genetic constraint (gnomAD): Loss-of-function variants: 41 observed, 72.03 expected, observed/expected ratio (o/e) 0.57, 90% interval 0.44 to 0.74. The upper end of that interval is the gene's LOEUF score, 0.74, which puts it in group 3 of 6, group 1 being the genes least tolerant of losing a copy. Missense variants: 586 observed, 719.36 expected, observed/expected ratio (o/e) 0.81, 90% interval 0.76 to 0.87. Synonymous variants: 295 observed, 281.8 expected, observed/expected ratio (o/e) 1.05, 90% interval 0.95 to 1.15.
Homologues: Orthologues: chimpanzee MPP3 (99% identical), macaque MPP3 (99% identical), dog MPP3 (95% identical), pig MPP3 (94% identical), rabbit MPP3 (92% identical), mouse Mpp3 (91% identical), rat Mpp3 (90% identical), guinea pig MPP3 (85% identical), zebrafish mpp3a (71% identical), zebrafish mpp3b (69% identical), Drosophila melanogaster metro (40% identical), Caenorhabditis elegans magu-1 (30% identical), and 2 more. Paralogues in human: MPP7 (55% identical), MPP4 (38% identical), PALS1 (34% identical), MPP2 (32% identical), PALS2 (31% identical), CASK (30% identical), MPP1 (24% identical).
Diseases named in the same sentence as MPP3 in open-access papers:
MPP3 is named in the same sentence as 21 diseases in open-access papers, as found by Europe PMC text mining. Sharing a sentence is not in itself a finding about the gene and the disease. The quoted sentences say what the papers report.
lung carcinoma (2 papers, 2017 to 2020). "In addition, there are reports that MPP3 and DAL-1 (differentially expressed in adenocarcinoma of the lung protein) interact with TSLC1 (tumor suppressor in lung cancer-1) and that these genes may play an important role in a TSG (Tumor-suppressor Genes) cascade that regulates cell growth." (PMID 32899814, 2020).
coronary artery diseases (1 paper, 2018). "For example, MPP3 and MPP9 are associated not only with gastric ulcer, but also with COPD, preeclampsia, and coronary artery diseases." (PMID 29861771, 2018).
gastric ulcer (1 paper, 2018). An ulcerated lesion in the mucosal surface of the stomach.
leukemia (1 paper, 2022). A malignant (clonal) hematologic disorder, involving hematopoietic stem cells and characterized by the presence of primitive or atypical myeloid or lymphoid cells in the bone marrow and the blood. "This contrasts with adult bone marrow, where transformation of HSCs results in CD41+ leukemia, while transformation of MPP2, MPP3, and MMP4 cells results in both CD41+ and Gr1+ leukemias, with Gr1+ cells being more predominate in the transformed MPP3 and MPP4 populations." (PMID 36136600, 2022).
malignant pleural mesothelioma (1 paper, 2025). A malignant neoplasm that arises from mesothelial cells in the pleura and shows a diffuse growth pattern. "In a kinome, CRISPR‐Cas9 knockout screen in which kinases in malignant pleural mesothelioma (MPM) cancer cells were targeted WEE1, AURKA, MPP3, MAP3K12, DGKD and SPEG could be identified as candidate genes." (PMID 40242936, 2025).
Sepsis (1 paper, 2023). Sepsis is defined as life-threatening organ dysfunction caused by a dysregulated host response to infection. "MPP3 to our knowledge has not been previously associated with SIRS or sepsis." (PMID 38332914, 2023). "SIRS-specific biomarkers MPP3, PLA2G7, GPR124 and ARHGEF10L correlated positively with each other and negatively with the sepsis-specific biomarkers and CRP." (PMID 38332914, 2023).
infection (3 papers, 2015 to 2022). The state of being infected such as from the introduction of a foreign agent such as serum, vaccine, antigenic substance or organism. "The CD48+ CD150− CD135− MPP3 subpopulation is the one that is most strongly associated with monocyte and granulocyte fates both at steady state and under regenerative conditions, including during infection-adapted myelopoiesis." (PMID 35336108, 2022). "LKS+ cells (containing LT-HSC, MPP2, MPP3 and MPP4 subpopulations) significantly rose in the spleen of the 7-day PCA2-infected mice, and dropped at 14-day post PCA2 infection." (PMID 34975887, 2021). "Infection alone produced an accumulation of MPP1, MPP2, MPP3, and MPP4 cells, and, as with HSCs, MPP1 and MPP2 cells accumulated to a lesser extent with infection plus imatinib compared to infection alone." (PMID 25822986, 2015).
tumor (2 papers, 2015 to 2017). "CADM1 is a tumor suppressor belonging to the immunoglobulin superfamily of cell adhesion molecule and forms a cell adhesion complex with an actin-binding protein, 4.1B, and a scaffold protein, MPP3, in the cytoplasm." (PMID 25780926, 2015). "Notably, the expression of either CADM1, 4.1B or MPP3 is lost in 11 of 12 lung tumor cell lines, suggesting that these proteins provide an important cascade for tumor suppressor." (PMID 25780926, 2015).
digestive tumours (1 paper, 2024). "Our analysis of PPI networks identified 11 hub genes (Myd88, Traf6, Irf7, Cdk4, Ccnd2, Mapkap1, Prr5, Mpp3, Serpinb6b and Pvrl3) that were implicated in digestive tumours." (PMID 38434966, 2024). "The PPI networks identified 10 hub genes that were implicated in digestive tumour immunotherapy target TIM-3 (Myd88, Traf6, Irf7, Cdk4, Ccnd2, Mapkap1, Prr5, Mpp3, Serpinb6b and Pvrl3)." (PMID 38434966, 2024).
infectious disease (1 paper, 2023). A disorder directly resulting from the presence and activity of a microbial, viral, or parasitic agent in humans. "In this context, it is likely that MPP3 will play an important role in amplifying myelopoiesis in other deregulated contexts such as infectious diseases and aging." (PMID 37115584, 2023).
MPP3 also shares sentences with these, for which no sentence is quoted: Arthritis (1 paper); breast carcinoma (1); cancer (1); esophageal cancer (1); gastritis (1); gastrointestinal disease (1); liver cancer (1); myeloid leukemia (1); myeloproliferative neoplasm (1); preeclampsia (1); synovitis (1).